SERTAD1 (SERTA domain containing 1)
Description:
Acts at E2F-responsive promoters as coregulator to integrate signals provided by PHD- and/or bromodomain-containing transcription factors. Stimulates E2F1/TFDP1 transcriptional activity. Renders the activity of cyclin D1/CDK4 resistant to the inhibitory effects of CDKN2A/p16INK4A.
Synonyms: TRIP-Br1; SEI1; TRIPBR1
Tractability: PROTAC: UniProt records ubiquitination sites on it.
Gene: Protein-coding gene on chromosome 19 (40,421,589 to 40,425,992, reverse strand). Ensembl gene ENSG00000197019.
Subcellular location (Human Protein Atlas): Golgi apparatus; Nucleoplasm
Gene Ontology:
Molecular function: protein binding; transcription coactivator activity
Biological process: positive regulation of cell population proliferation; regulation of cyclin-dependent protein serine/threonine kinase activity; positive regulation of DNA-templated transcription
Cellular component: cytoplasm; nucleus
Genetic constraint (gnomAD): Loss-of-function variants: 5 observed, 10.72 expected, observed/expected ratio (o/e) 0.47, 90% interval 0.24 to 0.98. The upper end of that interval is the gene's LOEUF score, 0.98, which puts it in group 4 of 6, group 1 being the genes least tolerant of losing a copy. Missense variants: 264 observed, 284.19 expected, observed/expected ratio (o/e) 0.93, 90% interval 0.84 to 1.03. Synonymous variants: 127 observed, 125.84 expected, observed/expected ratio (o/e) 1.01, 90% interval 0.87 to 1.17.
Homologues: Orthologues: chimpanzee SERTAD1 (99% identical), macaque SERTAD1 (99% identical), dog SERTAD1 (91% identical), pig SERTAD1 (91% identical), guinea pig SERTAD1 (89% identical), mouse Sertad1 (86% identical), rat Sertad1 (83% identical). Paralogues in human: SERTAD3 (30% identical).
Diseases named in the same sentence as SERTAD1 in open-access papers:
SERTAD1 is named in the same sentence as 41 diseases in open-access papers, as found by Europe PMC text mining. Sharing a sentence is not in itself a finding about the gene and the disease. The quoted sentences say what the papers report.
breast carcinoma (6 papers, 2016 to 2025). "SERTAD1 has been implicated in the metastatic spread of breast cancer cells by upregulation of the PI3K/AKT signaling cascade, partly via NEDD4-1-mediated PTEN ubiquitination." (PMID 35625886, 2022). "Further, SERTAD1 differential expression also associated with numerous cancer types such as breast cancer, colon cancer, lung cancer, brain tumors, renal cancer, leukemia and lymphoma." (PMID 30857225, 2019). "Taken together, these data suggest that SERTAD1 blockage sensitized breast cancer cells to the anti-cancer drug in both in vitro and in vivo." (PMID 35625886, 2022). "Previous findings suggested higher ROS levels in SERTAD1-inhibited breast cancer cells, which aligns with the higher mitochondrial content in SERTAD1-null MEFs and mtDNA in SERTAD1-blocked cells found in our study." (PMID 35625886, 2022). "The transcriptional profile of SERTAD1 in other cancer cell lines from the HPA database also supported that the mRNA expression of SERTAD1 was significantly upregulated in breast cancer cell lines, especially MCF7." (PMID 35625886, 2022). "Among various breast cancer cell lines, higher SERTAD1 expression was found in MCF7 and MDA-MB-231 in suspension than in adherent cell culture." (PMID 35625886, 2022). "Inhibition of SERTAD1 promoted the sensitivity of breast cancer cells to Dox and paclitaxel, leading to a significant reduction in tumor volumes of xenograft mice." (PMID 35625886, 2022). "Especially SERTAD1 and Parkin2 have shown significantly higher fold change 3.77 and 1.89 in breast cancers tissue compared to normal tissue respectively." (PMID 30857225, 2019). "On the other hand, higher expression of SERTAD1 showed significantly better outcome in relapse free survival (44.4 as compared to low expression 31) of breast cancer patients (RNA seq data set, n = 626, Logrank test p = 0.000032, HR = 0.72)." (PMID 30857225, 2019). "The most interesting fact is that we postulated expression analysis of SERTAD1 in breast cancer and we observed reciprocal results (high expression of SERTAD1 revealed higher overall survival, n = 626, Logrank test p = 0.1259) from other cancers." (PMID 30857225, 2019). "With the exception of different cancers, higher survival rate observed with higher levels of SERTAD1 in breast cancer patients." (PMID 30857225, 2019). "Indeed, Ki67 positive cells were much more abundant in wild-type control tumors compared to that of MCF7KD-SERTAD1, suggesting the promoting role of SERTAD1 in breast cancer cell proliferation." (PMID 35625886, 2022). "As SERTAD1 is found to be upregulated in cancer cells upon stressful stimuli, we speculated that SERTAD1 expression in breast cancer cells may differ under 2D vs. 3D conditions." (PMID 35625886, 2022). "Therefore, we have also elicited the cancer patient’s survival analysis based on the higher or lower expression of SERTAD1 which may appear baseline for development of fabulous and novel treatment strategies for various types of cancers including breast cancer." (PMID 30857225, 2019). "The role of SERTAD1, however, in anti-cancer drug resistance of breast cancer cells and regulation of cellular homeostasis has not been understood." (PMID 35625886, 2022). "Increased level of SERTAD1 has a significantly higher survival rate in the initial time period, but after 100 months slightly reduced OS (n = 26/Logrank-test p = 0.34) and RFS in HER2 positive breast cancer patients." (PMID 30857225, 2019). "SERTAD3 is homologous to SERTAD1 and is up-regulated in MCF7 breast cancer cell lines (FANTOM5)." (PMID 27632927, 2016). "The heat map generated from the DNA microarray data in breast cancer patients by bc-GenExMiner v4.5 program showed SERTAD1 positively co-expresses with the LYSOSOME_ORGANIZATION_AND_BIOGENESIS gene set and LYSOSOME gene set, suggesting the promoting role of SERTAD1 on lysosomal protein biosynthesis." (PMID 35625886, 2022).
glioma (4 papers, 2017 to 2020). A benign or malignant brain and spinal cord tumor that arises from glial cells (astrocytes, oligodendrocytes, ependymal cells). "Up-regulated genes included the glioma related genes SEC61G and LNX1 and the cell cycle related SERTAD1 and CCNH." (PMID 29163818, 2017).
gastric cancer (2 papers, 2019 to 2024). A primary or metastatic malignant neoplasm involving the stomach. "As reported, AP1G1 and SERTAD1 promote gastric cancer progression." (PMID 38600465, 2024). "And, lower expression of SERTAD1 predicted significant (n = 655, Logrank test p = 0.00011) enhanced overall survival of patients with ovarian cancer while there is no significant (n = 631, Logrank test p = 0.1866) differences observed in gastric cancer." (PMID 30857225, 2019).
lung carcinoma (2 papers, 2019 to 2022). "SERTA domain containing 1 (SERTAD1) plays roles in different types of cell death response and is regarded as a key nuclear transcription factor in carcinogenesis, including lung cancer." (PMID 36101745, 2022). "Pan-Lung cancer PIP-seq datasets showed alteration of SERTAD1 significantly reduced both lung (p = 0.0390) and mixed (p = 0.0687) patients overall survival." (PMID 30857225, 2019). "In lung cancer, SERTAD1 analyzes in 3885 querying samples among eight studies that showed 163 queried samples which have been altered in the pathway and gene set." (PMID 30857225, 2019).
myeloma (2 papers, 2019 to 2025). "SERTAD1 acts as a potential carcinogenic driver in most of the cancers such as invasive breast cancer, glioblastoma, teratoma, myeloma and pancreatic ductal carcinoma." (PMID 30857225, 2019).
ovarian carcinoma (2 papers, 2006 to 2019). A malignant neoplasm originating from the surface ovarian epithelium. "Results showed that cancer patients with higher SERTAD1 mRNA expression resulted worse overall survival in brain, colon, lung, blood and ovarian cancer than those with lower SERTAD1 levels." (PMID 30857225, 2019).
acute leukemia (1 paper, 2017). A clonal (malignant) hematopoietic disorder with an acute onset, affecting the bone marrow and the peripheral blood.
Alzheimer disease (1 paper, 2022). A progressive, neurodegenerative disease characterized by loss of function and death of nerve cells in several areas of the brain leading to loss of cognitive function such as memory and language. "SERTAD1, which appeared to be essential for neuron death in trophic support deprivation in vitro and in vivo and in models of DNA damage, was associated with Alzheimer’s disease." (PMID 35386281, 2022).
breast tumor (1 paper, 2019). "Following the current study by TCSBN correlation analysis of SERTAD1 in cancer and normal tissue, SERTAD1 significantly correlated with JOSD2 (Corr = 6.15) and UBE2S (Corr = 0.588) in breast tumor and normal tissue respectively." (PMID 30857225, 2019).
cardiomyopathy (1 paper, 2025). A disease of the heart muscle or myocardium proper. "In contrast, PPP1R15A and SERTAD1 lack research evidence supporting their association with cardiomyopathy." (PMID 40717095, 2025).
cervical cancer (1 paper, 2019). A primary or metastatic malignant neoplasm involving the cervix. "The inhibition of SERTAD1 results cell proliferation arrest in human nasopharyngeal cancer (CNE2), cervical cancer (CaSki) and melanoma (MeWo) cancer cell lines." (PMID 30857225, 2019). "Further, we dissected the protein expression of SERTAD1 and found SERTAD1 affects chemotherapeutic drug targeting human cancer via synthesized SERTAD1 decoy peptide in nasopharyngeal cancer (CNE2), Cervical cancer (CaSki) and melanoma (MeWo) cancer." (PMID 30857225, 2019).
experimental autoimmune encephalomyelitis (1 paper, 2024). An autoimmune demyelinating disease of the central nervous system that is produced experimentally in animals by the injection of homogenized brain or spinal cord in Freund's adjuvant. "In vitro, SERTAD1 knockout was associated with decreased IL-1β and IL-18 secretion, while in vivo loss of SERTAD1 attenuated peritonitis and experimental autoimmune encephalomyelitis (EAE)." (PMID 38763335, 2024).
glioblastoma (1 paper, 2019). The most malignant astrocytic tumor (WHO grade IV). "In addition, alteration of SERTAD1 exhibits greater possibility of dying from glioblastoma as reciprocal to other cancers." (PMID 30857225, 2019). "On the other hand, in the subset (merged cohorts of LGG and GBM, TCGA datasets), we observed almost 100% patient survival of glioblastoma patients with altered SERTAD1." (PMID 30857225, 2019).
leukemia (1 paper, 2012). A malignant (clonal) hematologic disorder, involving hematopoietic stem cells and characterized by the presence of primitive or atypical myeloid or lymphoid cells in the bone marrow and the blood. "Moreover, the up-regulation of genes involved in inhibition of apoptosis (e.g. MCL1) may promote the survival of leukemia cells with accumulated DNA damage and their expansion as suggested by an up-regulation of genes involved in cell cycle progression (AHR, AHR, TUBB2A, RAPGEF3, SERTAD1, FLT1)." (PMID 22848414, 2012).
liver cancer (1 paper, 2019). An epithelial or non-epithelial malignant neoplasm that arises from the liver. "Kaplan-Meier Plotter distinctly exhibited a higher expression of SERTAD1 significantly (Logrank test p = 0.0015, n = 364) reduced median overall survival (OS) of patients with liver cancer." (PMID 30857225, 2019).
lung adenocarcinoma (1 paper, 2019). A carcinoma that arises from the lung and is characterized by the presence of malignant glandular epithelial cells. "The most mutation sites located between 0 and 236 amino acids while lung adenocarcinoma and stomach adenocarcinoma showed the mutation hotspot in cyclic A binding domain which is near to the SERTA domain of SERTAD1." (PMID 30857225, 2019).
melanoma (1 paper, 2019). A malignant, usually aggressive tumor composed of atypical, neoplastic melanocytes. "In skin tissue, SERTAD1 correlated with DEDD2 (Corr = 0.687) in melanoma and normal skin tissue." (PMID 30857225, 2019).
mood disorder (1 paper, 2022). A cognitive disorder a disturbance in which the person's mood is hypothesized to be the main underlying feature. "We found a significant overlap for 6 hub genes (ADM, CITED2, IER5, NFKBIZ, SERTAD1, TNF) with similar co-expression and dysregulation patterns associated with mood disorder." (PMID 35386281, 2022).
sarcoidosis (1 paper, 2020). Sarcoidosis is a multisystemic disorder of unknown cause characterized by the formation of immune granulomas in involved organs. "Eight upregulated transcripts were common to sarcoidosis lung granulomas (CSF3, SERTAD1, MMP9, CCL19, BCL3, AREG, PTGS, F3)." (PMID 33276795, 2020).
skin cancer (1 paper, 2019). "The poor prognosis has been seen in most of cancer patients, including brain, colon, lung, ovarian and skin cancer patients with higher SERTAD1 expression was in line with the obtained data from Kaplan-Meier plotter analysis." (PMID 30857225, 2019).
uterine cancer (1 paper, 2019). Primary or metastatic malignant neoplasm involving the uterine corpus and/or the cervix. "Before investigate the correlation of SERTAD1 with other candidate genes between cancer and normal tissue, we detected SERTAD1 (highest 17%) mutated together with other genes through oncoprint analysis in uterine cancer." (PMID 30857225, 2019).
cancer (13 papers, 2010 to 2022). A tumor composed of atypical neoplastic, often pleomorphic cells that invade other tissues. "We further elucidated cancer risk (hazard rate) based on SERTAD1 mRNA levels in term of OS, DFS, DSS and RFS." (PMID 30857225, 2019). "After investigation of expression pattern and its role in cancer induction, further, we had analyzed the effect of mutation of SERTAD1 on numerous types of cancers." (PMID 30857225, 2019). "In fact, differential expression revealed that lower and higher expression of SERTAD1 nuclear factor is associated with cancers like lung, breast blood and so on." (PMID 30857225, 2019). "Differential expression of SERTAD1 is associated with a number of candidate genes in cancers as well as normal tissues." (PMID 30857225, 2019). "Nuclear transcription factor SERTAD1 is involved in many carcinogenesis processes through the interaction, association and correlation with the number of genes and performs as a key regulator in cancer progression." (PMID 30857225, 2019). "We determined that distinct PCDs can be induced by different doses of Dox; SERTAD1 suppresses sensitivity of MCF7 to anti-cancer drugs and regulates the synthesis of lysosomal proteins." (PMID 35625886, 2022). "In this study, we examined how SERTAD1 sensitized cancer cells to anti-cancer drugs and the role of SERTAD1 in lysosomal protein biosynthesis was also investigated." (PMID 35625886, 2022). "Suppressing SERTAD1 slightly increased mitochondrial activity in cancer cells, but the phenomenon was clearly observed in mouse embryonic fibroblasts (MEFs) from KO-SERTAD1 mice compared with wild-type controls." (PMID 35625886, 2022). "SERTAD1 also affects cancer cell survival and tumorigenesis by inducing ubiquitination and degradation of PTEN in a NEDD4-1-dependent manner." (PMID 35625886, 2022). "The role of SERTAD1 in cancers has been widely studied as it has a dual role in carcinogenesis and patient survival." (PMID 30857225, 2019). "Further, after the expression analysis of SERTAD1 with other genes, we next tried to elucidate the putative function and correlation of SERTAD1 using tissue and cancer specific biological network (TCSBN)." (PMID 30857225, 2019). "Oncomine dataset findings exhibited differential expression and gene rank of SERTAD1 (29 out of more than 1900 genes) among a number of sequenced genes in many cancers." (PMID 30857225, 2019). "With further screening 54 articles included in qualitative and meta-analysis based on SERTAD1 expression and cancer patient clinical outcomes." (PMID 30857225, 2019). "In the current meta-analysis, we wish to decipher the potential role of SERTAD1 as a tumorigenic factor as well as transcriptomic and translational biomarker for various types of human cancers." (PMID 30857225, 2019). "In meta-analysis, cancer patients with higher SERTAD1 mRNA fold resulted worse overall survival than those with lower SERTAD1 levels." (PMID 30857225, 2019). "In this regard, we also carried out a systematic analysis combining thousands of genes expression or copy number variation analysis published online, to appraise the expression pattern, potential functions and distinct prognostic value of SERTAD1 in cancers." (PMID 30857225, 2019). "This gene summary output gave us a clue to further elucidate the function of SERTAD1 in different types of cancers." (PMID 30857225, 2019). "Expectedly we found that SERTAD1 is altered in most of the cancers, including lung (>8%), breast (>2.5), uterine (15%), stomach (4%), and pancreas (15%) as well as skin (3%) cancer." (PMID 30857225, 2019). "Our results showed the elevated levels of SERTAD1 functioning as a cancer modulator, especially carcinogenic in nature in few cancers." (PMID 30857225, 2019). "Collectively, these data indicated a dire need to perform extensive survival analysis of cancer patients with respect to low and high expression of SERTAD1." (PMID 30857225, 2019).